RNU6-405P (RNA, U6 small nuclear 405, pseudogene)
Gene: Small nuclear RNA gene on chromosome 17 (16,691,798 to 16,691,907, forward strand). Ensembl gene ENSG00000252446.
Homologues: Orthologues: chimpanzee U6 (92% identical), macaque U6 (86% identical), mouse Gm22997 (75% identical), pig U6 (74% identical), pig U6 (71% identical), rat U6 (70% identical). Paralogues in human: RNU6-467P (99% identical), RNU6-1178P (91% identical), RNU6-819P (81% identical), RNU6-333P (80% identical), RNU6-490P (80% identical), RNU6-480P (79% identical), RNU6-774P (79% identical), RNU6-127P (78% identical), RNU6-1318P (78% identical), RNU6-38P (78% identical), RNU6-845P (78% identical), RNU6-1237P (77% identical), and 1282 more.